TLR7 (toll like receptor 7)
Diseases named in the same sentence as TLR7 in open-access papers (continued):
Sharing a sentence is not in itself a finding about the gene and the disease.
pancreatic cancer (continued). "Here we show that the TLR7/8 agonist 3M-011 is a potent adjuvant to radiotherapy in syngeneic and orthotopic mouse models of colorectal and pancreatic cancer that resulted in marked local and systemic antitumor activity." (PMID 25609199, 2015). "In contrast to tumor cells derived from our patients with pancreatic cancer, acquired tumor cell lines expressed only very low levels of TLR7 and TLR8." (PMID 26134824, 2015). "However, TLR7 expression appears to increase the number of cytotoxic immune cells in both murine and human pancreatic cancer specimen." (PMID 35536778, 2022). "This suggests a possible role of TLR7 inhibitors in the treatment of pancreatic cancer." (PMID 29462934, 2018). "However, it has been reported that the receptor expression is upregulated in human pancreatic tumor cells, its signaling regulates carcinogenesis, TLR7 ligation promotes tumor progression and TLR7 blockade protects against cancer development." (PMID 29462934, 2018). "Previously, we showed that TLR7 or -8 expression is associated with UICC stage in PDAC and stimulation increases tumor cell proliferation and resistance to the cytostatic agent 5-fluorouracil (5-FU) in pancreatic cancer cells." (PMID 27941651, 2016). "In the current study, we show that neither genetic deletion of TLR9 nor blockade of TLR7/9 using IRS 954 significantly altered the metabolic changes associated with pancreatic cancer cachexia." (PMID 26172047, 2015). "Interestingly, in the present study in pancreatic cancer we observed that TLR7 or TLR8 stimulation increased tumor cell survival and resistance to the chemotherapeutic substance 5-fluorouracil." (PMID 26134824, 2015). "This includes Bcl-2 in PANC1 pancreatic cancer cells stimulated with an agonist for TLR7 and TLR8." (PMID 26134824, 2015). "Notably, COX-2 expression was indeed upregulated in our investigated patient tumors and was associated with TLR7 and TLR8 positivity in specimens of pancreatic cancer and after stimulation of human PANC1 cancer cells." (PMID 26134824, 2015). "We observed that tumor cells in pancreatic cancer strongly expressed stage-dependent TLR7 and TLR8." (PMID 26134824, 2015). "Whether intracellular TLR7 and TLR8 expression, known to be associated with single stranded RNA (virus) infection in this context may be associated with recognition of pathogenic viruses in the investigated human pancreatic cancers remains speculative." (PMID 26134824, 2015). "PNP inhibitors additionally provide a novel approach for therapeutic TLR7 activation for use as a vaccine adjuvant or for treatment of immunologically cold malignancies with upregulated PNP expression, such as pancreatic cancer." (PMID 35653193, 2022). "We characterized the expression of TLR7 and TLR8 in several purchased human pancreatic cancer cell lines." (PMID 26134824, 2015). "We showed that stimulation of both receptors TLR7 and TLR8 in pancreatic cancer cells results in increased tumor cell proliferation and reduced chemosensitivity." (PMID 26134824, 2015). "To analyze the impact of the intracellular TLR7 and TLR8 expression in mediating inflammation in pancreatic cancer cells we first examined in the present study their expression in human tissues from primary pancreatic cancers." (PMID 26134824, 2015). "Increased COX-2 expression together with TLR7 and TLR8 positivity in pancreatic cancer cells was detected (top and below right, and B, respectively)." (PMID 26134824, 2015). "Our data demonstrate a stage-dependent upregulation of both TLR7 and TLR8 expression in pancreatic cancer." (PMID 26134824, 2015). "In the present study, we analyzed the expression of TLR7, TLR8, NF-κB and COX-2 in pancreatic cancer at different UICC stages and compared with chronic pancreatitis and healthy controls." (PMID 26134824, 2015). "In the present study, we determined the role of both TLR7 and TLR8 expression and signaling in tumor cell proliferation and chemoresistance in pancreatic cancer." (PMID 26134824, 2015).
pancreatic cancer (continued). "In contrast, global knockout of TLR7 expression in the well‐established KPC mouse model of pancreatic cancer did not result in attenuated tumor progression or increased survival of the mice." (PMID 36602302, 2023). "Several studies described a negative role of the TLR7 agonist, gardiquimod, in pancreatic cancer progression." (PMID 34884547, 2021). "Furthermore, in epithelial cells, TLR7 stimulation leads to multiple signaling activation, such as STAT3, Notch, MAP kinase and NF-κB in epithelial cells, confirming that pancreatic cancer is driven by stromal inflammation." (PMID 34884547, 2021). "Indeed TLR7, TLR8 and CD34 were positively expressed in pancreatic cancer and pancreatic cells from chronic pancreatitis cells, but not or at very low levels in normal pancreatic cells." (PMID 26134824, 2015). "Furthermore, upon stimulation with gardiquimod, TLR7 induces the expression of anticancer genes such as PTEN and tissue inhibitor of metalloproteinase 1 (TIMP-1) and it downregulates the expression of VEGF in BxPC-3 pancreatic cancer cells." (PMID 34884547, 2021). "Similarly, the absence of TLR7 on BM-derived cells reduced carcinogenesis in a pancreatic cancer model." (PMID 28300057, 2017). "However, to our knowledge neither TLR7 nor TLR9 has been studied in the treatment of pancreatic cancer cachexia." (PMID 26172047, 2015). "Thus, intracellular TLR7 and TLR8 signaling pathways in TLR7+ and TLR8+ expressing pancreatic cancer cells may have the potential to sustain cancer progression." (PMID 26134824, 2015). "TLR7 and TLR8 expression in pancreatic cancer, chronic pancreatitis, and normal pancreatic tissue was analyzed by immunohistochemistry in pancreatic tissue from patients with pancreatic cancer (UICC II and UICC III, n=48), chronic pancreatitis (n=8) and in normal pancreas (n=8)." (PMID 26134824, 2015).
dermatitis (23 papers, 2011 to 2025). An inflammatory process affecting the skin. "IMQ is an agonist of toll-like receptor 7 (TLR-7), inducing skin inflammation, and the inflicted skin condition has human Pso characteristics." (PMID 40869018, 2025). "Topical application of imiquimod — a TLR7 agonist that is widely used to treat genital warts and actinic keratosis — resulted in development of psoriasis-like dermatitis in mice." (PMID 35874756, 2022). "IMQ, a treatment for various skin disorders, acts through TLR7 to stimulate an immune response, with intense itching and painful burning commonly reported as side effects." (PMID 29561265, 2018). "To determine whether Sult2b1 expression and CS production are altered under psoriatic inflammatory conditions, we established an IMQ (toll-like receptor 7 agonist)-induced skin inflammation model." (PMID 41181147, 2025). "Expression of Tlr7 mRNA was constitutively observed and increased in mouse BMCMCs in response to imiquimod, and TLR7 on mast cells was responsible for development of imiquimod-induced dermatitis in mice." (PMID 35874756, 2022). "Taken together, these results indicate that JNK1 expression in the myeloid compartment contributes to Aldara®-induced skin inflammation through the IL-1β production system rather than by acting downstream of the TLR7 pathway." (PMID 33613525, 2020). "Though the IMQ model is well established and valuable murine psoriatic model, the vehicle of IMQ cream can activate skin inflammation that is independent of Toll-like receptor 7, such as inflammasome activation, keratinocyte death, and interleukin-1 production." (PMID 39737847, 2024).
Splenomegaly (23 papers, 2012 to 2025). Abnormal increased size of the spleen. "On the other hand, TLR7 knockdown caused serious splenomegaly in infected mice, according to our previous studies." (PMID 36279265, 2022). "TLR8−/− deficient mice were hypersensitive to TLR7/8 agonist treatment (R848), showing several indicators of inflammation, such as splenomegaly, increased serum levels of autoantibodies against dsDNA or ribonucleoprotein, and GN." (PMID 32660060, 2020). "Similar to TLR3 activation, TLR7/8 activation during pregnancy in mice caused pregnancy-dependent hypertension, endothelial dysfunction, splenomegaly, and an increased incidence of fetal demise." (PMID 22848646, 2012). "For instance, in mice suffering from chronic progressive inflammation causing splenomegaly, thrombocytopenia, and chronic active hepatitis due to spontaneous TLR7-dependent systemic inflammation, symptoms were alleviated through the use of anti-surface TLR7 antibodies." (PMID 33597952, 2020). "In conclusion, 12‐weeks of co‐treatment of TLR7 agonist IMQ with HFD exacerbated splenomegaly, hepatomegaly and impaired OGTT in female FVB/N mice." (PMID 38346802, 2024). "Tlr7 and Cybb double-KO mice had reduced splenomegaly, but only female mice had improved lymphadenopathy." (PMID 39042716, 2024). "Imq-treated pSS animals exhibited cervical lymphadenopathy, splenomegaly, and expansion of TLR7-expressing B cells." (PMID 36591307, 2022). "TLR7[Tg] and R2-Yaa animals exhibit splenomegaly and peripheral lymphocyte expansion of B cells and CD4+ T cells, but no significant peripheral CD8+ T cell expansion." (PMID 28098193, 2017). "In Slc29a3−/− mice, lysosomal nucleoside stress activates TLR7, leading to splenomegaly, whereas lysosomal RNA stress in Rnaset2−/− mice results in both hepatomegaly and splenomegaly, suggesting that RNA stress activate distinct responses compared with nucleoside stress." (PMID 39853307, 2025). "We did not detect any significant synergistic effects of a 42% kcal from fat HFD on the development of splenomegaly or autoantibodies in response to the TLR7 agonist in FVB/N mice in this 12‐week study, or in our previous 6‐week study of IMQ treatment of C57BL/6J mice." (PMID 38346802, 2024). "Thus, TLR7 agonism induces cervical lymphadenopathy, splenomegaly, and expansion of TLR7-expressing B cells in secondary lymphoid organs, and these changes are more pronounced in pSS mice as compared to healthy controls." (PMID 36591307, 2022). "The S. japonicum infection induced splenomegaly was increased in the infected TLR7 KO mice." (PMID 34788282, 2021). "Thus, HFD exacerbates splenomegaly in TLR8ko mice and this phenotype is TLR7-dependent since it is abrogated in TLR7/8ko mice." (PMID 31552019, 2019). "It has also been shown that the mice treated with the TLR7/8 agonist CLO97 exhibited pregnancy-dependent hypertenia, endothelial dysfunction, splenomegaly, and placental infection similar to the features of PE." (PMID 33535891, 2021). "We found that TLR7-stimulated B6 and NZM2410 mice had significantly reduced survival and exhibited profound splenomegaly with significantly reduced B cells (4 vs. 40%), and T cells (8 vs. 31%)." (PMID 31998321, 2019). "In contrast, broad human TLR7 expression under the CAG-Cre driver did not drive splenomegaly in WT and Slc29a3−/−Tlr7−/− mice." (PMID 37462944, 2023). "Similar to our study, treatment of male and female C57BL/6 mice with another TLR7 agonist, resiquimod, over a similar time-frame promoted splenomegaly, no significant rise in dsDNA autoantibodies but a significant increase in ANA." (PMID 35874527, 2022). "Both female and male TLR8ko mice at the age of 8- and 14-months had splenomegaly compared to WT controls, while TLR7/8ko mice did not." (PMID 34108972, 2021).
Splenomegaly (continued). "Surprisingly, the percent of B and T cells were both significantly decreased in TLR7-stimulated mice, regardless of strain; absolute numbers were also significantly decreased, despite significant splenomegaly in TLR-stimulated mice." (PMID 31998321, 2019). "However, 10-mo-old DNase II−/−Ifnar1−/− mice have been reported to develop splenomegaly and produce antinuclear antibodies in a STING- or AIM2-independent manner; instead, Unc93b, which regulates the localization of several TLRs (e.g., TLR3, TLR7, and TLR9) to the endosome, is required." (PMID 34901991, 2022).
glioma (22 papers, 2012 to 2025). A benign or malignant brain and spinal cord tumor that arises from glial cells (astrocytes, oligodendrocytes, ependymal cells). "We identified AD- and glioma-associated miR-9-5p, miR-132-5p, miR-340-3p, miR-30e-3p, miR-501-3p, and let-7b as ligands for human TLR7 and TLR8." (PMID 41322409, 2025). "Using a machine learning algorithm and the disease-linked database PhenoMiR, we identified Alzheimer’s disease (AD)- and glioma-associated miRNAs as ligands for TLR7 and TLR8." (PMID 41322409, 2025). "Longitudinal MRI and magnetic resonance elastography (MRE) were performed to monitor response to immunotherapy with a toll-like receptor 7/8 agonist in orthotopic syngeneic experimental glioma." (PMID 38971907, 2024). "We have recently shown the efficacy of the TLR7/8 agonist resiquimod when encapsulated in CDNP in a preclinical glioma model." (PMID 38971907, 2024). "Activation of TLR7 on gastric cancer cells triggers apoptosis, while activation of TLR7 on glioma cells and TLR4 on tumor cells triggers cell proliferation." (PMID 37296415, 2023). "Here, we investigate a β-cyclodextrin nanoparticle (CDNP) formulation encapsulating the Toll-like receptor 7 and 8 (TLR7/8) agonist R848 (CDNP-R848) to reprogram myeloid cells in the glioma microenvironment." (PMID 36774352, 2023). "This study demonstrated that CSC exosomes, releasing SNHG16, promoted glioma progression by activating the TLR7/MyD88/NFκB/c-Myc signaling pathway, suggesting those markers as possible targets for glioma treatments." (PMID 34638913, 2021). "TLR7 expression was significantly higher in the patient- and glioma cell line-derived TS than their adherent differentiated counterparts (ADCs)." (PMID 33431816, 2021). "Small molecule inhibition of lactate enabled the TLR7/8 agonist R848 to stimulate secretion of IL-12 by DC in the glioma environment thereby alleviating immune suppression." (PMID 25411122, 2014). "TLR7 can further modulate immune response and glioma cell growth." (PMID 41157253, 2025). "This indicates that TLR7 has minimal baseline activity and could potentially be targeted in glioma immunotherapy to induce immunostimulatory TLR7-mediated pathways." (PMID 36774352, 2023). "Another study found that let-7 family members function in a UUGU motif-dependent manner, as toll-like receptor 7 (TLR7) ligands to regulate tumor microglia: treatment with let-7b/e decreases growth of a murine glioma model by increasing microglial infiltration in a TLR7-dependent manner." (PMID 37370851, 2023). "We next tested whether activation of the TLR7/8 pathway by CDNP-R848 can control the growth of established orthotopic gliomas in a syngeneic mouse glioma model." (PMID 36774352, 2023). "In glioma, pDCs exhibit an impaired response to TLR7/9 stimulation and are defective in T-cell immunity and type I IFN secretion, resulting in regulatory T-cell (Treg) accumulation and immunosuppressive microenvironment, which further contributes to tumor progression and poor patient survival." (PMID 34715891, 2021). "In human and murine glioblastoma/glioma, differentially expressed let-7 miRNAs are signaling molecules that induce microglial inflammatory cytokine release, modulate antigen presentation, and attenuate cell migration in a TLR7-dependent manner." (PMID 34211501, 2021). "Based on the current literature, TLR3 and TLR7 agonists may be generally categorized as “safe” agonists to use in glioma therapy, as response is largely tumor inhibition in the absence of tumor promotion." (PMID 25411122, 2014). "While several studies report effects of TLR3, TLR7 and TLR8 signaling in gliomas, their overall roles remain context dependent and incompletely defined while the functions of TLR5 and TLR10 are largely underexplored." (PMID 41157253, 2025).
glioma (continued). "Up to date, TLR2, TLR3, TLR4, TLR7, and TLR9 have been intensely studied in glioma, while less or missing information is available regarding the mechanisms of TLR1/TLR6 (dimerizes with TLR2), TLR5, TLR8 (dimerizes with TLR7), and particularly TLR10." (PMID 34715891, 2021). "TLRs play an important role for the interaction of microglia with glioma cells promoting a pro-tumorigenic phenotype including TLR2, TLR4, and TLR7 signaling." (PMID 32912327, 2020). "Moreover, TLR2, TLR3, TLR4, TLR7, TLR8, and TLR9 have emerged as critical modulators of glioma biology." (PMID 41157253, 2025). "Within the family of TLRs, TLR-2, TLR-4, and TLR-9 stand out with unique expression patterns in glioma cell lines, while TLR-7 and 8 remain absent in gliomas." (PMID 39202716, 2024). "We find that sustained release of TLR7/8 agonist leads to clearance of residual post-resection tumor, improved survival, and subsequent protection from tumor challenge in mice bearing orthotopic GL261 or CT2A gliomas." (PMID 39399681, 2024). "Several studies have found that increased TLR7 and TLR9 expression in glioma tissues is related to poorer prognosis, while TASL is located downstream of TLR7-9, which indirectly supports the conclusion that high TASL expression is related to poor prognosis of LGG." (PMID 37296415, 2023). "The coinjection of SHG44 and U251 cells with exosomes from SNHG16-overexpressing CSCs into nude mice promoted glioma progression, whereas the inoculation with SHG44 and U251 transfected with si-TLR7 or si-MyD88 reverted those effects by decreasing NFκB activity and c-Myc expression." (PMID 34638913, 2021). "The experiments using the GL261 glioma mouse model were prompted by our previous results on the promotion of tumor growth involving TLR2, TLR4, and TLR7 signaling, and were driven by the assumption that TLR5 might detect host-derived molecules." (PMID 32912327, 2020). "The adenosine receptor-mediated signaling pathway may be responsible for IMQ's ability to limit tumor growth because its inhibitory effects on glioma cells are independent of TLR7 expression." (PMID 40727443, 2025). "Furthermore, researchers have developed a β-cyclodextrin nanoparticle (CDNP) formulation encapsulating the TLR7/8 agonist R848 (CDNP-R848), which reprograms myeloid cells in the glioma microenvironment to induce regression of syngeneic experimental gliomas and significantly improve survival rates." (PMID 41488647, 2025). "TLR7/TLR8 are not expressed in the CNS-1 rat model of glioma, according to a different study." (PMID 40727443, 2025). "As an endogenous TLR7 ligand, miR‐1983 activates TLR7 in pDC and cDC via the 5′‐UGUUU‐3′ motif at its 3′ end and further activates downstream signaling, stimulating IFN‐β secretion via MyD88‐IRF5/IRF7, and ultimately eradicating gliomas through stimulation of NK cells." (PMID 37170647, 2023). "Up to date, TLR7/8 expression was found absent in glioma cell lines (CNS-1 and GL-261), and TLR10 has unknown ligand and was poorly investigated." (PMID 34715891, 2021). "The inhibitory effects of IMQ in glioma cells do not require TLR7 expression, and the mechanism by which IMQ inhibits tumor growth could be due to the adenosine receptor-mediated signaling pathway." (PMID 31240216, 2019). "Similarly, another study found that TLR7/TLR8 is not expressed in the glioma rat model CNS-1; however, the activation of TLR7/8 by R848 alone was sufficient to cause rejection of the smaller established glioma in CNS-1." (PMID 31240216, 2019). "The impact of TLR3, TLR5, TLR7, TLR8, and TLR10 signaling in glioma development is not fully elucidated." (PMID 34715891, 2021).